IFNG (interferon gamma)
Diseases named in the same sentence as IFNG in open-access papers (continued):
Sharing a sentence is not in itself a finding about the gene and the disease.
tumor (continued). "The final multi-omics model incorporated the following 10 initial genomic and transcriptomic biomarkers: response pathway, nsTMB, HED, fsIndel burden, defects in B2M, HLA-B27 supertype, tumor purity, TCR α chain entropy, IFNG-IMS ratio, and IGH entropy." (PMID 40075562, 2025). "Compared to patients with high LAMP2A expression, those with low LAMP2A expression showed significantly increased tumor-infiltrating CD8+T cells and IFNγ expression, indicating a favorable response to PD-1 monoclonal antibody treatment." (PMID 40083918, 2025). "Studies have shown that dietary tryptophan depletion reduces AhR activity in TAMs and promotes the accumulation of TNFα+IFNγ+ CD8+ T cells within tumors, thereby enhancing anti‐tumor immune responses." (PMID 40314129, 2025). "The protein levels of IFNγ and CD8 in tumor tissues were remarkably increased confirmed by western blot, which partially reflected the activation of cytotoxic CD8+ T cells." (PMID 40270598, 2025). "This reduction led to an increase in the infiltration of pro-inflammatory, tumor-fighting CD8+ T cells producing TNFα and IFNγ, suggesting that tryptophan metabolism by Lactobacillus can modulate immune responses in PDAC, potentially affecting tumor growth." (PMID 40927726, 2025). "Overall, we concluded that a direct effect of IFNγ on proliferation and indirect effect on MHC-I expression and subsequent killing by CD8+ T cells contribute to the selection of WT over IFNγRKO tumour cells in our admix model." (PMID 39746898, 2025). "The tumor killing by M002-treated CD4+ T cells required MHCII signals, and also CD4+ T-cell-derived IFNγ that increased MHCII expression on tumor cells, forming a positive feedback loop." (PMID 39885128, 2025). "Supernatant collected from this experiment revealed that IFNγ release was increased with LTA vaccination compared to placebo control and that increased release was specific to tumor-stimulated conditions." (PMID 41042672, 2025). "This was further confirmed by elevated IFNγ+ and TNFα+ cytotoxic CD8+ T cells within the Cyp11a1cKO tumour milieu." (PMID 40287432, 2025). "Bystander killing of TAA‐negative tumor cells has been reported to involve tumor necrosis factor (TNF) and IFNγ." (PMID 40178291, 2025). "Indoleamine 2,3-dioxygenase 1 (IDO-1) and interferon-gamma (IFN-γ) are proteins that play a significant role in inflammatory conditions and tumor development." (PMID 40710094, 2025). "Liver sinusoidal endothelial cells (LSECs) enhance disseminated tumor cell (DTC) retention by expressing adhesion molecules and releasing nitric oxide (NO) and interferon-gamma (IFN-γ), which can induce apoptosis in tumor cells entering the sinusoids." (PMID 41002563, 2025). "The combination of vaccine and ICI also promoted IFNγ, IL2, and granzyme B production in the tumor microenvironment, suggesting enhanced activation of antigen-specific T cells." (PMID 41012179, 2025). "Consistently, EZH2i promoted T cells activation (Granzyme B, IFNγ) and inhibited their exhaustion (LAG3) in tumor treated with chemotherapy, with similar phenomena as chemoimmunotherapy." (PMID 40708008, 2025). "Interferon Regulatory Factor (IRF) mediates critical responses to interferon gamma (IFN-γ), a key cytokine in anti-tumor immunity." (PMID 40565027, 2025). "CAR-T cells activation and B-cell tumor lysis both result in release of TNF-α and interferon gamma (IFN-γ)." (PMID 39812904, 2025). "Our study suggests that sequestration of IAP1 by LKB1 helps maintain a functional IFNγ-JAK-mediated immune response in LKB1-WT cells, whereas, in LKB1-mut cells, IAP1 directly impinges on JAK1 and impairs tumor immune response." (PMID 40057483, 2025). "Eosinophils can enhance CD8 T cell recruitment and tumor cytotoxicity by promoting TNF-α and IFNγ signatures, potentially leading to prolonged overall survival, regardless of treatment type." (PMID 40386779, 2025).
tumor (continued). "M1 macrophages, which secrete pro-inflammatory cytokines like lipopolysaccharide (LPS) and interferon-gamma (IFN-γ), combat cancer, whereas M2 macrophages produce cytokines that support anti-inflammatory responses and aid in tumor progression." (PMID 39561105, 2025). "Dazostinag and radiation also resulted in induction of peripheral and intratumoral IFNγ and recruitment of proliferating CD8+ T cells to tumor, suggestive of an increased adaptive immune response compared with 0-hour C1D1." (PMID 41296842, 2025). "Compared with IFNγ, TNFA in NLRP4-OE tumor interstitial fluid (TIF) manifested consistent up-regulation regardless of CD8+ T cells deletion." (PMID 40087771, 2025). "IL-4 contributes to tumor growth via several mechanisms, including reducing interferon-gamma (IFN-γ) production and upregulating anti-apoptotic genes in tumor cells, supporting their survival and growth." (PMID 40864740, 2025). "However, IFNγRKO tumour volumes were surprisingly equivalent to that of WT tumours when NK cells were depleted, suggesting that NK cells did not provide enhanced control of tumours with low MHC-I and that other immune cells might be involved in controlling IFNγ-insensitive tumours." (PMID 39746898, 2025). "NK cell-specific deletion of Regnase-1 (Reg1ΔNK) increased cytolytic activity and interferon-gamma (IFN-γ) production in vitro and increased intratumoural accumulation of Reg1ΔNK-NK cells in vivo, reducing tumour growth in an IFN-γ-dependent manner." (PMID 41429765, 2025). "Given the increased expression of GzmB, IFNγ and TNFα by M002-treated CD4+ T cells, and their tumor reactivity, we next determined if these CD4+ T cells were capable of mediating killing of tumor cells beyond their conventional helper activity." (PMID 39885128, 2025). "Our upcoming studies will also evaluate the interplay between TNFα, IFNγ, PGE2, and alternative NF-κB in regulating the balance between the pro- and anti-tumor functions of different myeloid cell types." (PMID 41142824, 2025). "Further analysis of marker gene expression revealed that Tfh and Treg cells in the low AA group expressed higher levels of markers characteristic of IFNG+ Tfh cells and TNFRSF9+ Treg cells, which are identified as key tumor-reactive subclusters." (PMID 40475762, 2025). "T-cells anti-tumor activity exerted by CD8+ compartment involves the release of IFNγ which sensitizes cancer cells to ferroptosis, probably due to the ability of IFNγ to inhibit SCL7A11." (PMID 41339932, 2025). "It was recently shown that oxidized and desialylated LDL suppresses anti-tumor responses by lymphokine-activated killer (LAK) cells, e.g., cell cytotoxicity and IFNγ production." (PMID 40563926, 2025). "Cytokine signaling, in turn, involves the activity of interferon-gamma (IFN-γ), which activates the JAK/STAT pathway, leading to increased expression of MHC molecules and PD-L1 on tumor cells." (PMID 40563651, 2025). "Interferon Gamma (IFNG) is a cytokine with both pro- and anti-tumor effects, serving as a predictive marker for immunotherapy efficacy." (PMID 40236693, 2025). "The TIDE score is a tool developed for estimating the efficacy of tumor immune checkpoint therapies and is calculated on the basis of the presence of CAFs, MDSCs, and TAM M2 immune cells and the levels of CD8, IFNG, dysfunction and other indicators." (PMID 41262242, 2025). "To verify the anti-tumor role of NK cells in Rag2-/- mice, we performed FACS analysis to examine infiltration of the interferon gamma (IFNγ) producing NK cells in tumors treated with vehicle and indisulam for 3 days, respectively." (PMID 40962798, 2025). "CD8(+) T cells are very important in cancer immunotherapy because they produce IFNγ, which activates the STAT1 signalling pathway, inhibits SLC7A11 expression and induces ferroptosis in tumour cells." (PMID 39865544, 2025).
tumor (continued). "Immunotherapy advances include engineered bone marrow-derived mesenchymal stem cells (BMSCs) delivering sPD1 and IFNγ, which enhance T cell activation, suppress PI3K/AKT/PD-L1 pathways, and promote tumor cell senescence." (PMID 40781676, 2025). "Consistent with observations in the murine system, overexpression of hA1R on human anti-Lewis Y CAR T cells enhanced the production of IFNγ and TNF by CAR T cells upon coculture with either OVCAR-3 or MCF7 (both Lewis Y+) tumor cells." (PMID 40610421, 2025). "We confirmed that the 3D growth of tumor cells and the expression of CXCL5 were increased by the conditioned media from IFNγ + TNFα co-treated macrophages, similar to those of IFNγ + LPS stimulation." (PMID 40050422, 2025). "Functional assessments demonstrated that while both the DAP12-containing CAR and its predecessors exhibited comparable tumor-killing, the DAP12 construct produced lower levels of IFNγ, TNFα, and IL-2, during tumor cell lysis." (PMID 40948803, 2025). "By treating NCI-H1299 cell line and primary tumor cells (obtained from patients) with the ferroptosis inducer RSL3, the authors observed increased sensitivity to IFNγ secreted by ROR1 CAR T-cells." (PMID 41339932, 2025). "This signature includes key genes for maintaining cellular cytotoxicity such as ZNF683,41PRF1, IL2RB, and IFNG and immune activation and exhaustion markers including LAG3, PDCD1, PRF1, and TBX21 that contribute to anti-tumor immunity." (PMID 41045934, 2025). "Radiotherapy, through IFNγ-driven changes, enhances T-cell recruitment and tumor antigen presentation by increasing MHC class I expression on tumor cells." (PMID 40723238, 2025). "Cancer cells can upregulate PD-L1 under the influence of interferon-gamma (IFN-γ), delivering inhibitory signals to T cells and thereby evading anti-tumor immunity." (PMID 41488641, 2025). "The blockade of the CD6-CD318 interaction by itolizumab increases the cytotoxic capacity of CD8 T and NK cells over CD318+ tumor lines, reverses the NKG2A/NKG2D ratio, and increases granzyme B and IFNγ production." (PMID 40391211, 2025). "In particular, it suppressed Ki67+CD8+, TNFα+CD8+, and IFNγ+CD8+ T cells while restoring PD‐1+CD8+ and TIM‐3+CD8+ T cells in tumor lesions." (PMID 39903759, 2025). "Conversely, cytotoxic T lymphocytes (CTLs), natural killer (NK) cells, and dendritic cells (DCs) release cytokines such as interferon gamma (IFN-γ) and interferon alpha (TNF-α) to identify and eliminate tumor cells, thereby inhibiting tumor growth." (PMID 39941048, 2025). "For example, the SCFAs pentanoate and butyrate can modulate the anti-tumor immune response by enhancing the production of TNFα and IFNγ by cytotoxic CD8 T cells, thus enhancing their anti-tumor activity." (PMID 41368640, 2025). "Nevertheless, we observed a significant increase in the IFNγ expression in both CD4- and CD8-positive T cells infiltrating tumors, which was attributed to the anti-tumor activity that slowed the tumor growth." (PMID 40361381, 2025). "In particular, the treatment induced elevated production of interferon gamma (IFN-γ), enhanced activity of NK cells and CD8+ T lymphocytes and promoted tumor infiltration by immune cells." (PMID 41002413, 2025). "We examined cytokine secretion profiles (IL-2, IL-4, IL-6, and IFNG) from activated T cells (CD69, IL-2RA, CD38, and HLA-DRB1) to evaluate T-cell activation in the CM tumor microenvironment, revealing consistently low expression levels." (PMID 40959090, 2025). "These lymphocytes are responsible for synthesizing various cytokines, such as interferon-gamma (IFN-γ), which are essential for activating macrophages and inducing an effective immune response against tumor cells." (PMID 40733498, 2025). "Anti-CD40 antibodies exert tumor-suppressive effects by engaging tumor-infiltrating macrophages and increasing levels of CCL2 and IFNγ, thereby enhancing tumor cell elimination." (PMID 40343509, 2025).
tumor (continued). "As pro-inflammatory cytokines, IFNγ and TNF-α promote other immune cell activation and can induce tumor cell apoptosis." (PMID 39179536, 2024). "Together, these insights point to a regulatory interplay between IFNγ and MHC-II in HPV+ tumor cells, which potentially promotes the anti-tumor T cell immunity." (PMID 39105803, 2024). "Expressions of inflammatory cytokine (IFNγ) and T lymphocyte activation (CD25) were also examined in the tumor-infiltrating CD8 T cells, and were significantly increased in mice receiving ACT of CD44high CD8 T cells from the FLT3L-treated OT-1 mice." (PMID 38287325, 2024). "Despite the collaborative efforts of immune cells to disrupt tumor vessels, particularly through the activity of IFNG-secreting CD8+ T cells and M2 macrophages, tumor angiogenesis still impacts the infiltration of CD8+ T cells." (PMID 38397971, 2024). "Clones with different IFNγ sensitivity were inoculated in C57BL/6 mice and assessed for tumor outgrowth." (PMID 39009951, 2024). "Both IFNγ and GZMB are well known for their direct cytotoxic effects on tumor cells and being able to stimulate production of immune-stimulating cytokines." (PMID 39618825, 2024). "Several signaling pathways, including Notch, IFNγ, and WNT, display alterations in the expression of their molecular components—such as ligands, receptors, and transcription factors—that facilitate tumor growth." (PMID 39735530, 2024). "In contrast, a number of studies have shown that CD276 inhibits anti-tumor immunity, including suppression of CD4+ and CD8+ T cell activation and proliferation, and reduction of IL-2 and IFNγ production." (PMID 38637557, 2024). "The results showed that, with the exception of SMIM24, which was highly expressed in normal tissues, PLCB2, HLA-DQB2, IFNG, and XCR1 were all highly expressed in tumor tissues." (PMID 39273185, 2024). "In the acquired tumor lesions, high CD8+/mm2 and relatively high IFNγ signature levels were observed." (PMID 38280045, 2024). "IFNγ stimulates the expression of antigen-presenting MHC-I, which is crucial for the host response to intracellular pathogens and tumor cells by facilitating T-cell recognition and cytotoxicity." (PMID 38920249, 2024). "Sin3B‐deficient tumor cells exhibited amplified CXCL9/10 secretion in response to Interferon‐gamma (IFNγ), creating a positive feedback loop via the CXCL9/10‐CXCR3 axis, thereby intensifying the anti‐tumor immune response against PDAC." (PMID 39316363, 2024). "We first evaluated the effects of IFNγ signaling on the AML cells and tumor microenvironment using AUCell39." (PMID 38418901, 2024). "To evaluate the requirement for IFNγ in antitumor responses driven by FS120m treatment, we treated MC38 tumor–bearing C57BL/6 mice with FS120m or isotype control and anti–IFNγ-blocking antibody." (PMID 38995700, 2024). "The robust induction of IFNγ suppressed both TGFβ-dependent SMAD3 activation and CCKAR-AKT signaling–mediated collagen expression in the tumor microenvironment." (PMID 39574893, 2024). "After the antitumor effect of the combination therapy was eliminated by the depletion of gut microbiota, Bacteroides fragilis increased tumor-infiltrating CD3+ T cell, NK cell, IFNγ+ CD8+ T cells and elevated the level of isobutyric acid (IBA)." (PMID 39251538, 2024). "When we compared tumor Teff 1 with normal Teff 1, we observed an increased level of GNLY, GZMB, and IFNG was accompanied by higher HAVCR2 (TIM-3)." (PMID 39454432, 2024). "Small molecule AKT activator, SC79, impaired the growth of poor immunotherapy responder murine tumours, B16 and EMT-6 suppressing CD4+Foxp3+Treg TILs through the conversion of Tregs to IFNγ+CD4+Th1-like T cells." (PMID 38704478, 2024). "These modified MSCs recruit and activate natural killer (NK) cells and macrophages, boosting interferon-gamma (IFN-γ) and CXCL10 levels in the tumor microenvironment." (PMID 39796040, 2024).
tumor (continued). "Th1 cells secrete cytokines like interferon-gamma (IFN-γ) and tumor necrosis factor-alpha (TNF-α), promoting cytotoxic T cell proliferation and tumor cell eradication." (PMID 39906672, 2024). "The IFNγ-mediated PD-L1 expression by ECs was suitable for CD8+ T cell inhibition, making it a possibility for tumor cells to drive immune escape." (PMID 39033271, 2024). "Consistently, a higher proportion of tumor‐infiltrating T cells exhibited expression of the T cell activation marker CD69 and effector molecules GZMB and IFNγ in the combination treatment group as compared with to the control or single drug treatment group." (PMID 39412086, 2024). "FC analysis of the tumor tissues revealed that knockdown of CXCL1 combined with PD-1 antibody treatment markedly augmented the amount of CD8+ T cells and IFNγ+ cells and reduced the abundance of MDSCs." (PMID 38510750, 2024). "Tumor-infiltrating B-lymphocytes (TIL-Bs) In metastatic ovarian tumors, TIL-Bs secrete GM-CSF, IFNγ, IL-12p40, CXCL10, and IL-7, which stimulate macrophages, T cells, and dendritic cells (DCs)." (PMID 39068459, 2024). "Under the ambiance of HPV+ tumor cells, CD4+T cells manifested an upregulated expression of CXCL13 and IFNγ, indicating the enhanced differentiation toward CXCL13+ CD4+ T cells and TH1 phenotype." (PMID 39105803, 2024). "The S-UMAP analysis revealed highly significant correlations between EpCAM in lymphoid restricted regions, where elevated IFNγ and NOS2 were expressed, either at the tumor edge or in tumor satellites areas." (PMID 39356141, 2024). "Inhibiting neutrophils or NETs enhances the expression of cytotoxic proteins like IFNγ and TNFα in CD8+ T cells, resulting in better tumor control." (PMID 39648199, 2024). "Interaction with peptides presented by MHC I on tumor cells induces CD8 T cells to produce cytolytic factors, granzyme and perforin, and cytokines IL-12, IL-2 and IFNγ that act to kill tumor cells." (PMID 38474178, 2024). "By contrast, ATO treatment promoted the accumulation of tumor-infiltrating CD8+ T cells and increased the proportion of IFNγ+ cells in the CD8+ T cell population." (PMID 38684648, 2024). "Subsequent flow cytometry analysis revealed that the combination therapy of STM2457 with anti‐PD‐1 reduced CD8+ T‐cell exhaustion in B16 tumours and significantly enhanced CD8+ T‐cell cytotoxicity by upregulating the expression of IFNγ and GzmB." (PMID 39568154, 2024). "Upon co-incubation with CD19-expressing tumor cells, the activation of NFκB and NFAT, the upregulation of CD69, CD25 and 4-1BB, and the secretion of IFNγ and TNF were severely impaired by the phospho-mimicking CAR variants compared to the WT CAR." (PMID 38779683, 2024). "In CD8+ T cells, IL6 upregulates immune checkpoints like PD-1, diminishing cytotoxic function and reducing the production of key cytokines, such as interferon-gamma (IFN-γ), thereby impairing anti-tumor responses." (PMID 39766086, 2024). "Interaction with HPV+ OPSCC tumor cells amplifies CXCL13 and IFNγ release in CD4+T cells, fostering a pro-inflammatory TME." (PMID 39105803, 2024). "Comparing tumor reactivity from bulk CD8+ T cell populations of CB versus dBM, we noted intra-individual differences in IFNγ release and tumor cell-killing ability." (PMID 39085419, 2024). "Snapshots from the simulations show distinct dynamics of IFNγ secretion, CD8+ T cell proliferation, and tumor killing as well as different spatial phenomena relating to tumor phenotype." (PMID 38636457, 2024). "This potent tumor inhibition was impaired by TRA knockout, suggesting that stimulation of both IFNγ-inducing signals is needed to treat ECM-rich solid tumors." (PMID 39574893, 2024). "In AKR tumor samples, we also observed increased proportion of activated CD8+ T population (CD69 and IFNγ) in Trp63-knockdown tumors." (PMID 38509096, 2024).